KLF4 (KLF transcription factor 4)
Diseases named in the same sentence as KLF4 in open-access papers (continued):
Sharing a sentence is not in itself a finding about the gene and the disease.
viral infection (9 papers, 2016 to 2025). "Immunofluorescence analysis further demonstrates enhanced viral infection in KLF4 knockout cells relative to wild-type cells." (PMID 40867674, 2025). "KLF4 plays crucial roles in regulating viral infections and host immune responses by binding to the promoters of immune genes such as interferon β (IFNβ), Z transactivator (BZLF1), and R transactivator (BRLF1)." (PMID 31382472, 2019). "Moreover, translocation of KLF4 from cytosol to nucleus was observed upon viral infection and concomitant inhibition of ISRE and NF-κB-mediated transcription." (PMID 41155497, 2025). "Moreover, ChIP analysis after viral infection confirmed recruitment of KLF4 to the IFNB gene promoter in a competitive fashion with IRF3." (PMID 41155497, 2025). "While overexpression of KLF4 in transient assays can activate both early and late reporters, in viral infections KLF4 are low in undifferentiated cells and high in differentiated layers suggesting KLF4’s primary effect may be to regulate the late viral promoter upon differentiation." (PMID 27386862, 2016). "The transcriptional regulator Krüppel-like factor 4 (KLF4), which is widely expressed in human tissues, increasingly localises to the nucleus after viral infection where it binds to the IFNβ promoter region." (PMID 32645843, 2020). "Next, we infected KLF4 knockout and wild-type cells with PEDV and assessed viral infection." (PMID 40867674, 2025). "Both Akata virus infection and AG876 virus infection decrease the expression levels of numerous different differentiation markers induced by methylcellulose suspension in uninfected NOKs, including K10, involucrin, GHRL3, ZNF750, KLF4, TGM1 and SPRR1A." (PMID 36190982, 2022). "Using the EdU flow cytometry cell proliferation assay, we found that overexpression of KLF4 with adenovirus (AdKLF4) exhibited a higher percentage of mgR SMCs undergoing replication (8.36%) compared to both no viral infection (mgR) or an empty vector control (AdEmpty) (6.96 and 6.64, respectively)." (PMID 29040313, 2017).
Hypertension (8 papers, 2021 to 2025). The presence of chronic increased pressure in the systemic arterial system. "Our findings demonstrate the associations of KLF4 and KLF5 genetic variants with hypertension risk, as well as the indicative roles of mRNA expression levels of KLF4 and KLF5 in hypertension and antihypertensive treatment." (PMID 39187911, 2024). "The current study demonstrated the associations of KLF4 and KLF5 genetic variants with hypertension, as well as the association of the indicative variations in mRNA expression levels of KLF4 and KLF5 with the risk of hypertension and antihypertensive treatment." (PMID 39187911, 2024). "Individuals with high blood pressure have increased levels of KLF4 mRNA; however, after taking antihypertensive drugs, the KLF4 mRNA levels decreased." (PMID 39187911, 2024). "The results showed a concurrent increase in SIAT7A and KLF4 levels in hypertrophic myocardium of essential hypertension patients and in hypertrophic cardiomyocytes stimulated by Ang II." (PMID 39431583, 2024). "In this study, we observed a concurrent increase in SIAT7A and KLF4 levels in the hypertrophic myocardium of patients with essential hypertension, rats and Ang II‐induced hypertrophic AC16 cells." (PMID 39431583, 2024). "We also showed that miR‐145 inhibited the differentiation of AD‐VSMCs by increasing KLF4 degradation or reducing KLF4 expression; these changes delayed the progression of hypertension‐induced aortic wall remodeling and further suppressed the occurrence of AD." (PMID 34767671, 2021). "On one hand, hypertension orchestrated a discerning in situ proliferation and transcriptional activation in specific cardiac resident macrophage states, guided by Kruppel-like factor 4 (KLF4)." (PMID 40585349, 2025).
medulloblastoma (8 papers, 2012 to 2022). A malignant, invasive embryonal neoplasm arising from the cerebellum. "On the other hand, KLF4 was identified as a tumor suppressor, owing to frequent loss of expression in medulloblastoma and colon, esophageal, gastric, bladder, pancreatic, and lung cancers." (PMID 22937066, 2012). "A methylated CpG island in the −2154 to −1796 bp region of the KLF4 promoter was detected in medulloblastoma." (PMID 24551169, 2014). "KLF4 is inactivated by either genetic or epigenetic mechanisms in a large subset of medulloblastomas, and it likely functions as a tumor suppressor gene in the pathogenesis of medulloblastoma." (PMID 24551169, 2014). "Reduced KLF4 expression was shown to undergo promoter methylation and loss of heterozygosity (LOH) in gastrointestinal cancer and medulloblastoma." (PMID 22937066, 2012). "KLF4 is not only a critical regulator of monocytic differentiation, but has been shown to be pathologically inactivated in medulloblastoma, and recently to interact with miR-10b in transition to oesophageal cancer." (PMID 22348345, 2012).
oral cancer (8 papers, 2015 to 2024). "This study demonstrated that KLF4 gene promoter was hypermethylated in oral carcinoma cells at a different region from other-types of carcinoma cells, and that it was associated with KLF4 expression." (PMID 26847634, 2016). "This study demonstrated that hypermethylation at a narrow range of the promoter region down-regulates KLF4 expression, and suggests that the loss of expression by the hypermethylation contributes to oral carcinoma progression." (PMID 26847634, 2016). "Taken together, these findings indicate that KLF4 expression promotes oral cancer cell migration and invasion, which is associated with MMP-9 expression." (PMID 26517087, 2015). "However, another study suggested that the downregulation of KLF4 is associated with the progression of oral carcinoma." (PMID 37559082, 2023). "KLFs transcriptionally regulate target gene expression through binding on the promoter, and previous studies documented that loss of KLF4 expression associates with dedifferentiation of oral carcinoma cells and is frequently observed in an aggressive subset of the carcinomas." (PMID 26847634, 2016). "Since loss of KLF4 expression closely associates with oral carcinoma progression, restoring the expression may be an intriguing strategy to treat the patients." (PMID 26847634, 2016). "KLF4 is mainly located in the nucleus, but its cytoplasmic localisation has also been reported in prostate and oral cancers." (PMID 37559082, 2023). "A 237-bp promoter region spanning − 718 and − 482 of KLF4 gene was hypermethylated in oral carcinoma cells that express KLF4 at a low level, but the methylation was infrequent in cells expressing KLF4 high amount." (PMID 26847634, 2016). "Genomic DNA isolated from nine different oral carcinoma cell lines and a normal keratinocyte line was treated with sodium bisulfite, and methylation at KLF4 gene promoter was determined by PCR direct-sequence analysis." (PMID 26847634, 2016). "In this study, we analyzed the hypermethylation and correlation with KLF4 expression in oral carcinoma cells." (PMID 26847634, 2016). "In fact KLF4 is down-regulated in less-differentiated and advanced oral carcinomas and suppresses dedifferentiation of the cells." (PMID 26847634, 2016). "Hypermethylation responsible for gene inactivation is frequently observed in CpG islands of tumor suppressive genes, and it was shown in KLF4 gene in this study, suggesting that the region is important to regulate KLF4 expression in oral carcinoma cells." (PMID 26847634, 2016). "This study investigated the epigenetic alterations and possible roles of KLF4 in oral cancer carcinogenesis." (PMID 26517087, 2015). "These in vitro and in vivo results suggest that KLF4 plays a tumor suppressive role in oral cancer development." (PMID 26517087, 2015). "Although the in vitro and in vivo data revealed the Janus-faced character of KLF4, which acted both as a tumor suppressor and as an oncogene in oral cancer development and progression." (PMID 26517087, 2015). "Knockdown of KLF4 promoted oral cancer cells growth and colony formation, and simultaneously inhibited cell migration and invasion." (PMID 26517087, 2015). "Taken together, these in vitro and in vivo data revealed that KLF4 can play a positive role by acting as a tumor suppressor in oral cancer development." (PMID 26517087, 2015). "Since KLF4 is tumor suppressive, its inactivation by the promoter hypermthylation may be a mechanism of oral carcinoma progression as in carcinoma cell lines analyzed in this study." (PMID 26847634, 2016). "Sp1 plays a critical role in epithelial development, and Klf4−/− mice develop oral carcinomas." (PMID 26847634, 2016). "Moreover, KLF4 promoter methylation was also observed in oral cancer cell lines and oral cancer tissues, and this methylation played an important role in KLF4 down-regulation." (PMID 26517087, 2015). "Although much is known about KLF4, its role is not fully understood in oral cancers." (PMID 26517087, 2015).
oral cancer (continued). "Notably, KLF4 expression was significantly decreased in human oral cancer tissues compared with healthy controls, and KLF4 promoter hypermethylation contributed to the suppression of KLF4 expression." (PMID 26517087, 2015). "In addition, KLF4 over-expression promoted oral cancer cell migration and invasion in vitro." (PMID 26517087, 2015). "Querying the TCGA HNSCC dataset we identified 8 potential mRNA targets (ESM1, KLF4, IL8, CCL20, IL24, CCNA1, TIMP4 and MMP1) from our validated 20 mRNA panel, which were aberrantly expressed in HNSCC and controlled by CELF1 in oral cancer cells." (PMID 26498364, 2015). "Krüppel-like factor 4 (KLF4) is a transcription factor regulating proliferation-differentiation balance of epithelium, and down-regulated in less-differentiated and advanced oral carcinomas." (PMID 26847634, 2016).
prostate tumor (8 papers, 2015 to 2025). "To further study the link between KLF4 and its targets AR and miR-1 in clinical samples, we analyzed 22 independent prostate tumor tissue samples collected from the Wan Fang Hospital, Taipei Medical University (Taiwan)." (PMID 27991915, 2016). "Taken together, all findings above demonstrated that miR-7 restoration inhibits overall prostatic tumor growth in vitro and in vivo mainly due to suppression of the stemness factor KLF4." (PMID 26172296, 2015). "All these data indicated that inhibition of overall prostatic tumor growth by miR-7 was achieved via suppression of KLF4." (PMID 26172296, 2015). "For example, KLF4 serves as a prostate tumor suppressor but plays a role in PCSC homeostasis." (PMID 36428807, 2022). "KLF4 is highly expressed in indolent tumors which do not cause any symptoms and do not require any treatment but is absent from aggressive prostate tumors." (PMID 33266506, 2020). "In primary prostate tumors, examinations on tissue samples from age matched patients by immunohistochemistry showed that KLF4 protein is expressed in the vast majority of epithelial cells in BPH as well as in PCa, whereby PCa exhibited lower KLF4 expression as BPH." (PMID 29017567, 2017). "Interestingly, while in germ cell tumors, NANOG is a relevant transcript, in prostate tumors, KLF4 is a relevant stem marker." (PMID 27901106, 2016). "Thus our findings demonstrated that miR-7 inhibits overall prostatic tumor growth by suppression of KLF4/PI3K/Akt pathway." (PMID 26172296, 2015). "By suppression of KLF4 and its downstream PI3K/Akt/p21, miR-7 impairs PCSCs' stemness and overall prostate tumor growth." (PMID 26172296, 2015). "Therefore, we further determined whether miR-7 restoration inhibits overall prostatic tumor growth also through attenuation of PI3K/Akt pathway and whether such attenuation is mediated by KLF4." (PMID 26172296, 2015). "Interestingly, by considering all prostate tumors together without a separation in TUR-BPH, RP-BPH and RP-PCa, we found a highly significant correlation between KLF4 and IGF2 expression (p < 0.0001, Spearman’s rank correlation coefficient r = 0.668)." (PMID 29017567, 2017).
psoriasis (8 papers, 2014 to 2025). An autoimmune condition characterized by red, well-delineated plaques with silvery scales that are usually on the extensor surfaces and scalp. "Other loci related to the IL-17/IL-23 axis and involved in psoriasis susceptibility correspond to genes coding for IL-6, with a protective effect, or KLF4 genes." (PMID 37628670, 2023). "Taken together, the 3C results confirm a close spatial proximity between the psoriasis-associated SNPs and KLF4 in 9q31.2." (PMID 32366252, 2020). "Our CHi-C data showed significant interactions (CHiCAGO score ≥ 5) between the psoriasis association and the promoter of KLF4 in both unstimulated and stimulated HaCaT cells, over a distance of approximately 560 kb." (PMID 32366252, 2020). "At the intergenic locus 9q31.2, the psoriasis association falls between two distant gene clusters where the suggested gene candidate was Krüppel-like factor 4 (KLF4) due to its relevant biological functions in differentiation and innate immunity." (PMID 32366252, 2020). "For one locus, uniquely, we combine further epigenomic evidence to demonstrate how a psoriasis-associated region forms a functional interaction with the distant (> 500 kb) KLF4 gene." (PMID 32366252, 2020). "We used 3C-qPCR in an effort to confirm the interaction between the psoriasis-associated putative enhancer 3 (rs6477612) and KLF4 and to further prioritise regulatory SNPs." (PMID 32366252, 2020). "The KLF4-focused 3C experiment showed that KLF4 significantly interacted with several intergenic psoriasis-associated fragments, including the fragment containing the third putative enhancer (rs6477612), in HaCaT cells, but not in My-La cells." (PMID 32366252, 2020). "In the intergenic 9q31.2 psoriasis risk locus, we implicate KLF4 as the likely causal psoriasis risk gene in this region by its functional interaction with the psoriasis GWAS variants." (PMID 32366252, 2020). "Enhancer activity in 9q31.2 is increased after IFN-γ stimulation, correlating with an increase in KLF4 gene expression, although we were unable to detect increases in H3K27ac occupancy at the tested psoriasis-associated enhancer regions." (PMID 32366252, 2020). "Krüppel-like factor 4 (KLF4) is a transcription factor associated with psoriasis." (PMID 34639182, 2021). "We employed CRISPRa in 9q31.2 to determine whether activating the psoriasis-associated enhancers could impact on gene expression (KLF4 or other, more distal genes), implicating a functional role for the long-range interactions." (PMID 32366252, 2020). "In summary, by combining the HiChIP, CHi-C 3C and ChIP evidence, we could determine that the psoriasis-associated enhancer region interacts with KLF4 in both My-La and HaCaT but is only active in HaCaT cells." (PMID 32366252, 2020). "The CHi-C experiment showed long-range interactions between the psoriasis-associated SNPs and KLF4." (PMID 32366252, 2020). "With respect to KCs, we identified an AP-1 motif enriched with respect to sequences near genes co-expressed with KLF4 (P = 2.3 × 10−3), and found that a linked psoriasis risk variant at rs7850481 (543 kb upstream of KLF4) abrogated a match to this motif (Part E)." (PMID 24885462, 2014). "KLF4 has only rarely been mentioned to be related to inflammatory diseases, but is known as a regulator of proinflammatory cytokine expression in rheumatoid arthritis, and is one of the susceptibility genes for psoriasis, 2 diseases in which IL-36γ is significantly increased in the inflamed tissues." (PMID 31805013, 2020). "Importantly, CRISPRa of the psoriasis-implicated enhancer in this keratinocyte cell line not only resulted in an increase in KLF4 expression, but a differential expression of 3 keratin genes (keratin 4, 13 and 15), confirming the importance of this enhancer and the KLF4 gene in skin cell function." (PMID 32366252, 2020).
psoriasis (continued). "miR-135b-5p is also reported to target KLF4, an important transcription factor in skin barrier formation; a pathway that is disrupted in psoriasis." (PMID 34068434, 2021). "It was especially notable, therefore, when a recent psoriasis GWAS meta-analysis uncovered associations that implicated genes functioning within the innate immune system (e.g., DDX58, KLF4, ZC3H12C, CARD14 and CARM1)." (PMID 24885462, 2014). "Another example of a daSNV that alters binding of the JUN TF is the psoriasis SNV rs10217259, which is looped to the KLF4 gene promoter." (PMID 40998781, 2025). "Psoriasis-like changes in DEGP expression were also observed in fibroblasts transduced with OKSM reprogramming factors (OCT4, KLF4, SOX2, c-MYC), demonstrating pathway-level overlap between psoriasis and induced pluripotency." (PMID 26251673, 2015).
B-cell lymphomas (7 papers, 2015 to 2026). "The epigenetic silencing of KLF4 in B‐cell lymphomas, particularly in classical Hodgkin's lymphoma (CHL), is thought to bolster lymphoma survival through the relaxation of cell‐cycle constraints and protection from apoptosis." (PMID 41532367, 2026). "Primary cases of B-cell lymphomas revealed that the KLF4 promoter was methylated, thus silencing the expression of KLF4 in the B cells." (PMID 40831570, 2025). "In this regard, KLF4 has been reported to exert growth suppressive effects in B-cell non-Hodgkin lymphoma, yet a recent study found that high nuclear expression of KLF4 in Burkitt pediatric lymphoma was indicative of inferior overall survival." (PMID 26109433, 2015). "KLF4 was identified as a tumor suppressor in B‐cell lymphoma." (PMID 41532367, 2026). "In the 2010s, research has predominantly focused on exploring the role of KLF4 in B‐cell lymphoma." (PMID 41532367, 2026).
depression (7 papers, 2020 to 2024). "Serum levels of testosterone, estradiol, and depression risk biomarkers (thyroid hormone, lipids, hs-CRP, Tenascin-C [TNC], GDF15, KLF4, Gas6, and sgp130) were measured." (PMID 36635686, 2023). "Additionally, GWAS-PW identified three regions showing high probability of shared associations between depression and ER + BC, including two regions near 6p22.2 (6p22.1, PPA_3 = 0.71; 6p22.3–22.2, PPA_3 = 0.89), and one region at 9q31.2 (PPA_3 = 0.52, harboring a previous-reported BC locus KLF4)." (PMID 37143087, 2023). "Kruppel-like factor-4 (Klf-4) and dual-specificity phosphatase-1 (Dusp-1) are known to be negative regulators of the mitogen-activated protein kinase (MAPK) cascade, and the function of this cascade decreases in depression." (PMID 33327458, 2020).
diabetic nephropathy (7 papers, 2018 to 2025). "Restoration of KLF4 expression in murine podocytes of a diabetic nephropathy model caused a sustained decrease in proteinuria." (PMID 34630127, 2021). "Berberine counteracts this dysregulation by inhibiting DNMT1 and DNMT3a expression in the kidney tissues of diabetic nephropathy mouse models, thereby preventing methylation of the KLF4 promoter, enhancing KLF4 transcription, and ameliorating renal injury." (PMID 41471379, 2025). "It was previously reported that KLF4 expression decreases fibrotic responses in renal tubular epithelial cells during diabetic nephropathy." (PMID 31597574, 2019). "Similarly, the immunofluorescence staining on renal biopsy samples from patients with minimal change disease, focal segmental glomerulosclerosis, and diabetic nephropathy showed decreased glomerular expression of KLF4." (PMID 29747407, 2018). "We examined the expression of KLF4 in the adriamycin (ADM) nephropathy model, the puromycin aminonucleoside nephropathy model, and the db/db diabetic nephropathy model, and a decrease in KLF4 expression was observed in all models." (PMID 29747407, 2018). "And transcription factors HIF1α, KLF4, KLF5, RUNX1, SP1, VDR, WT1 may be also related to diabetic nephropathy." (PMID 34735495, 2021). "Transcription factors HIF1α, KLF4, KLF5, RUNX1, SP1, VDR and WT1 may be related to diabetic nephropathy." (PMID 34735495, 2021).